TLR4 (toll like receptor 4)
Diseases named in the same sentence as TLR4 in open-access papers (continued):
Sharing a sentence is not in itself a finding about the gene and the disease.
endothelial dysfunction (continued). "For example, it has been shown that in patients with allograft endothelial dysfunction (an early clinical indicator of transplant vasculopathy), mRNA transcript level and surface expression of TLR-4 on circulating monocyte is significantly higher than controls." (PMID 21234308, 2010). "Finally, two other studies failed to designate any role of the Asp299Gly Toll-like receptor 4 polymorphism on endothelial dysfunction, or an association of the rs10116277 or rs1537375 SNPs of the 9p21.3 genomic region with cIMT or carotid plaques." (PMID 35680906, 2022). "A TLR4 antagonist might reduce systemic inflammation and endothelial dysfunction induced by the EBOV-shed GP, a putative TLR4 agonist, without interfering with the initiation of protective responses via other intracellular innate immune receptors, such as RIG-I." (PMID 26425845, 2015). "TLR4 could also contribute to endothelial dysfunction by reducing NO production." (PMID 25093580, 2014). "LPS activates TLR4–NF-κB/MAPK signaling and upregulates pro-inflammatory cytokines and the inducible enzyme COX-2, thereby promoting endothelial dysfunction." (PMID 41009419, 2025). "This allows lipopolysaccharides (LPS) to translocate throughout the body and activate Toll-like receptor 4 (TLR4) signaling, leading to endothelial dysfunction and chronic inflammation." (PMID 41515210, 2025). "The binding of HMGB1 to receptors such as TLR2, TLR4, and RAGE triggers inflammatory pathways that contribute to endothelial dysfunction and vascular inflammation." (PMID 40361188, 2025). "Actually, ex vivo study on cultured endothelial cells exposed to sera of HD patients showed that inflammasome proteins such as TLR4 and NALP3 contribute to the development and perpetuation of endothelial dysfunction in response to the uremic toxicity." (PMID 40943876, 2025). "Our present data indicate that endothelial dysfunction is mediated by TLR4 activation, since the drug CLI 095, which specifically inhibits TLR4-mediated signalling, prevented the defective relaxations induced by visfatin/eNampt." (PMID 32214150, 2020). "Released during necrosis, apoptosis, and neutrophil extracellular trap (NET) formation, histones act as damage-associated molecular patterns (DAMPs), engaging receptors such as Toll-like receptors (TLR2, TLR4, TLR9) to trigger endothelial dysfunction, platelet activation, and cytokine release." (PMID 41993174, 2026). "Through its engagement with key receptors, notably TLR4 and CAP-1, resistin activates a cascade of proinflammatory signaling pathways, including NF-κB and MAPK, which drive endothelial dysfunction, promote leukocyte adhesion and migration, and initiate early atherosclerotic processes." (PMID 41347124, 2025). "This could lead to the activation of Toll-Like Receptor 4 (TLR4) and release of adhesion molecules and cytokines, which could contribute to worsening endothelial dysfunction." (PMID 40332185, 2025). "Our previous study indicated that the endothelial dysfunction induced by TBI might be due to the overacting of TRPC6 channels, which could be activated by some increased levels of chemokine through TLR4." (PMID 35203995, 2022). "Furthermore, the result of overexpressed TLR4 and HIF‐1α was the same as vivo experiment, reversing the effect of resveratrol on inhibiting Gly‐LDL‐induced endothelial dysfunction." (PMID 34114347, 2021). "In fact, this observation unveils that the activation of TLR4 by visfatin/eNampt or NMN may trigger differential and time-dependent signals to ultimately provoke endothelial dysfunction." (PMID 32214150, 2020). "Interestingly, pharmacological TLR4 inhibition also prevented CNI upregulation of ET-1 mRNA expression, a key factor involved in the endothelial dysfunction." (PMID 27295076, 2016).
endothelial dysfunction (continued). "Lipopolysaccharides (LPS) from Gram-negative bacteria can also contribute to endothelial dysfunction by triggering systemic inflammation and activating toll-like receptor 4 (TLR4) signaling pathways, promoting endothelial cell damage and increasing vascular permeability." (PMID 40283011, 2025). "In the endothelium of blood vessels, LPS activate Toll-like receptor 4 (TLR4) receptors and macrophages to release pro-inflammatory cytokines, which may lead to endothelial dysfunction, plaque formation and rupture, as well as the oxidation of LDL and thrombogenesis." (PMID 31437200, 2019).
myocardial ischemia (83 papers, 2007 to 2025). A disorder of cardiac function caused by insufficient blood flow to the muscle tissue of the heart. "Previous studies have found that TLR4 plays a crucial role in mediating acute myocardial dysfunction caused by myocardial ischemia." (PMID 41155364, 2025). "Previous studies have reported that TLR4 regulates PGC‐1α after myocardial ischemia and that TLR4 abundance is associated with HSPB1 level." (PMID 38420163, 2024). "Reports also suggest the involvement of TLR4 in the pathophysiology of acute cardiac dysfunction, which is caused by septic shock as well as myocardial ischemia." (PMID 37239362, 2023). "TLR4 upregulation was also associated with high levels of ROS and increased production of iNOS that led to damage of the myocardium and to myocardial ischemia-related injuries." (PMID 37239362, 2023). "The TLR4/NF-κB signaling pathway has also been reported to be associated with vaspin-mediated cardioprotective effects on myocardial ischemia/reperfusion injury." (PMID 31072368, 2019). "TLR4-deficient mice sustained smaller infarctions and exhibited less inflammation compared to wild type mice after myocardial ischemia-reperfusion injury induced by 1 hour of coronary ligation followed by 24 hours of reperfusion." (PMID 21048961, 2010). "It has been reported that Toll-like receptor 4 (TLR4) deficiency reduces infarct size after myocardial ischemia/reperfusion (MI/R)." (PMID 17592640, 2007). "In the context of inflammation and its regulation during myocardial ischemia/reperfusion (MI/R) injury, TLR4 has been identified as a key mediator, with its deficiency shown to significantly reduce MI/R‐induced damage, lipid peroxidation, and complement deposition." (PMID 40551496, 2025). "In addition, the Toll-like receptor 4/ Nuclear factor-kappa B (TLR4/NF-kB) signaling pathway is implicated in generating inflammatory responses and the pathophysiology of myocardial ischemia injury via modulating pro-inflammatory cytokine production." (PMID 35944026, 2022). "Furthermore, TLR4 activation resulted in reduced cardiac function in mice whereas TLR4 deficiency promoted survival and reduction in septic shock and myocardial ischemia-induced cardiac dysfunction." (PMID 32850883, 2020). "However, necrotic cardiac myocytes due to myocardial ischemia release endogenous DAMPs, which is associated with a significant induction of TLR4 expression." (PMID 29538462, 2018). "The specific function of TLR4 in regulating the immune response to heart epitopes we describe here could be useful for treating autoimmune inflammatory conditions underlying human heart disease or cardiac ischemia-reperfusion injury." (PMID 24586934, 2014). "Tumor Necrosis Factor-alpha (TNF-alpha) has been identified as the principal cytokine induced by Toll-like receptor 4 (TLR4) in the pathophysiology of myocardial ischemia-reperfusion (I/R) injury." (PMID 40386784, 2025). "Overall, tilianin suppresses NLRP3 inflammasome activation in myocardial ischemia/reperfusion injury by inhibiting the TLR4/NF-κB and NEK7/NLRP3 pathways." (PMID 39508038, 2024). "With regard to myocardial ischemia/reperfusion (I/R) injury, studies performed on mouse models have revealed significant increases in TLR4 and NF-κB expression levels in both the ischaemic zone and the potential danger region." (PMID 38790263, 2024). "In myocardial ischemia/reperfusion infarction, the cross signaling between Axl and TLR4 in cardiac macrophages directed a switch from glycolysis to lipid metabolism and the secretion of proinflammatory IL-1β." (PMID 39684449, 2024). "Various studies have shown that TLR4 plays an important role in myocarditis, myocardial ischemia, myocardial infarction, and other myocardial injuries." (PMID 36903542, 2023).
myocardial ischemia (continued). "Taken together, these studies and our report further suggest an important role for TLR4 in cardiac ischemia–reperfusion injury; therefore, it is worthwhile to investigate the mechanisms of iron death and the role of TLR4 in this process." (PMID 38049739, 2023). "MSC-Ex can regulate macrophage polarization via miR-182 and inactivate TLR4/NF-κB/PI3K/Akt signaling cascades to alleviate myocardial ischemia/reperfusion (I/R) injury." (PMID 37303049, 2023). "Improvement in microcirculation after myocardial ischemia/reperfusion in STZ-induced diabetic animals treated with MP via TLR4/NF-κB signaling inhibition has been reported." (PMID 35872886, 2022). "It exerted anti-inflammatory effects and attenuated myocardial ischemia-induced injury by inhibiting the TLR4/NF-κB/NLRP3 signaling pathway." (PMID 35664944, 2022). "TLR4/NF-κB signaling pathway plays an important role in cardiomyocyte inflammation and apoptosis and can be targeted to alleviate myocardial ischemia/reperfusion injury and diabetic cardiomyopathy." (PMID 36114541, 2022). "TLR4 is a primary receptor of the innate immune system and plays a vital role in the induction of the inflammatory response in myocardial ischemia." (PMID 36247184, 2022). "Compared with the sham operation group, the myocardial ischemia-reperfusion injury group showed significant increases in TLR4, NF-KB, IL-1β, TNF-α, and IL-6." (PMID 34093716, 2021). "Current studies have shown that the rapid increase of TLR4 and NF-kB can occur during transient cardiac ischemia." (PMID 34093716, 2021). "Whereas, targeting TLR4 or downstream effectors of TLR4 such as MyD88 showed protective effects in many heart failure models, namely, myocardial ischemia and pressure overload." (PMID 33159115, 2020). "In fact, inhibition of TLR4/TRIF signaling cascade reportedly protected the heart in mice models of cardiac ischemia/reperfusion injury." (PMID 33324685, 2020). "Through a series of experiments on H9C2 cells, we verified that CLE can suppress myocardial ischemia-reperfusion injury by stimulating TLR4 and downstream PI3K/Akt signaling pathways to protect myocardial cells." (PMID 32116705, 2020). "In the current study, we investigated the effects and potential mechanism of HXP on myocardial ischemia and cardiac inflammation and the activation of TLR4/NF-κB pathway." (PMID 32695212, 2020). "TLR4 is expressed in the heart and up-regulated during myocardial ischemia/reperfusion (I/R) injury." (PMID 32116705, 2020). "Previous studies reported that TLR4/NF-κB signaling cascades contributes to VA under myocardial ischemia condition." (PMID 32733242, 2020). "We have previously demonstrated that IL-37 suppresses TLR-4 expression in murine myocardial ischemia/reperfusion injury." (PMID 31686988, 2019). "In particular, De Castro and coworkers demonstrated a critical role for T3 and T4 treatment in blunting the activation of the Toll-like receptor 4 (Tlr4)/NF-kB pro-inflammatory axis at two weeks following myocardial ischemia." (PMID 31295805, 2019). "Inhibiting the activation of TLR4/NF-κB signaling pathway contributes to reducing the expression of many pro-inflammatory cytokines and mitigating myocardial ischemia." (PMID 31816891, 2019). "PS also attenuates inflammation in rat heart due to cardiac ischemia through TLR4/NF-κB signaling pathway." (PMID 26762881, 2016). "This study also demonstrated cardioprotective action of resveratrol by inhibiting toll-like receptor 4 (TLR4)/NF-κB signaling pathway in a rat model of myocardial ischemia and reperfusion (MI/R)." (PMID 26697434, 2015). "Following revascularization, TLR4 activation was significantly reduced, meaning that increased TLR4 expression is reversible and correlated with the degree of cardiac ischemia." (PMID 26030867, 2015). "Whereas TLR4 has shown to play a detrimental role in myocardial ischemia/reperfusion (I/R) injury, the effect elicited by TLR2 activation remains controversial." (PMID 25566092, 2014).
myocardial ischemia (continued). "The regulation of TLR4 expression was showed in a model of myocardial ischemia/reperfusion, where TLR4 is up-regulated." (PMID 22233532, 2012). "Innate immunity is involved in myocardial ischemia/reperfusion (MI/R) injury, specifically through activation of TLR4, which was originally proposed to solely recognize lipopolysaccharide (LPS)." (PMID 17592640, 2007). "All cardiac cells express Toll-like receptors (TLR) 2–4 and TLR6, with TLR4-bearing cells activated via a TLR4 signal due to oxidative stress and the accumulation of activated complement during myocardial ischemia reperfusion, which triggers the onset and development of an inflammatory response." (PMID 39368019, 2025). "Additionally, berberine inhibited HMGB1/TLR4 signaling, reducing pro-inflammatory cytokines and cardiomyocyte inflammation in myocardial ischemia." (PMID 40525842, 2025). "Notably, berberine has been shown to inhibit the HMGB1/TLR4/NF-κB pathway in other inflammatory diseases, such as myocardial ischemia and neuroinflammation." (PMID 40525842, 2025). "TLR4 regulates PGC‐1α after myocardial ischemia, which has been verified in a recent study." (PMID 38420163, 2024). "Moreover, HMGB1, another RBP, plays a role in myocardial ischemia–reperfusion injury by triggering cardiomyocyte apoptosis through the TLR4 axis, promoting the release of cytokines and mediation of the inflammatory response via HMGB1/TLR4-related pathways." (PMID 37858115, 2023). "The TLR4/NF-κB signaling pathway is an important inflammatory signaling pathway involved in the pathophysiological processes of cardiovascular diseases such as cardiac ischemia, ventricular remodeling, fibrosis, and heart failure." (PMID 36903542, 2023). "Interestingly, MSC-Exo attenuates myocardial ischemia-reperfusion injury by enhancing M2 macrophages polarization through miRNA-182 and its downstream target, namely, toll-like receptor 4 (TLR4)." (PMID 34603289, 2021). "Similarly, resveratrol inhibits the inflammatory response after MIRI by inhibiting the expression of TLR4 and NF-kB, thereby reducing myocardial ischemia-reperfusion injury." (PMID 34093716, 2021). "Our previous study indicated that CLE could inhibit the expression of TLR4 in myocardial tissue, reduce myocardial ischemia-reperfusion injury and plays a role in myocardial protection." (PMID 32116705, 2020). "Continuous expression of TLR4, one of the major TLRs expressed by myocardial cells, was enhanced significantly in the myocardium after acute myocardial ischemia injury and participated in signaling pathways, particularly implicated in proinflammatory response by activating NF-κB pathway." (PMID 32695212, 2020). "We hypothesize that the mechanism of salvianolic acid B against myocardial ischemia may be related to the inflammatory cascade induced by TLR4/NF-κB/NLRP3 signaling pathway." (PMID 31816891, 2019). "Studies have shown that TLR4-mediated signals may induce myocardialdysfunction during myocardial ischemia/reperfusion." (PMID 29658970, 2018). "A prior study showed that when Toll-like receptor 4 was mutated or deficient, the rate of cardiomyocyte apoptosis and the infarct size decreased, with the expression of HMGB1 and TNF-α notably inhibited following myocardial ischemia/reperfusion." (PMID 25780404, 2015). "TLR4 can modulate myocyte contractility, myocardial ischemia-reperfusion injury." (PMID 20202224, 2010). "Many factors generated during early reperfusion are missing in an animal model of permanent myocardial ischemia, and these clinically relevant factors may elaborate the TLR4-mediated inflammatory responses and ECM protein remodeling in the remote non-ischemic myocardium." (PMID 25823011, 2015). "The targeted pharmacologic inhibition of TLR4 in the clinical setting of myocardial ischemia and reperfusion could initially lead to a smaller infarct, but an altered inflammatory response could have unexpected effects on cardiac function and long term infarct healing." (PMID 17592640, 2007).